MMP9 (matrix metallopeptidase 9)
Diseases named in the same sentence as MMP9 in open-access papers (continued):
Sharing a sentence is not in itself a finding about the gene and the disease.
melanoma (continued). "Acidosis has also been demonstrated to increase the secretion of proteases such as cathepsin B in melanoma cells and matrix metalloproteinase-9 (MMP-9) in human osteosarcoma cells, which may facilitate the degradation of extracellular matrix proteins and subsequently accelerate tumor cell invasion." (PMID 24367336, 2013). "Extensive research has been concentrated on identifying and developing MMP inhibitors for cancer treatment, including melanoma, with particular focus on MMP‐2, MMP‐9 and MMP‐14." (PMID 41546170, 2026). "It modulated melanoma cell metastasis by reducing MMP‐2 and MMP‐9 expression through the inhibition of the FAK/PI3K/Akt/mTOR, MAPK and GRB2 signalling pathways." (PMID 41546170, 2026). "MMI‐166, a third‐generation inhibitor targeting MMP‐2 and MMP‐9, demonstrated reduced tumour proliferation in mice injected with B16‐BL6 melanoma cells." (PMID 41546170, 2026). "As well as curcumin, imatinib, and thalidomide have all been shown to inhibit melanoma VM, concomitant with decreases in EPHA2, VE-cadherin, PI3K, VEGF, HIF-1, MMP-2, and MMP-9 expression and/or activity." (PMID 40507830, 2025). "In melanoma (B16-F10 and A375) cells, emodin decreases MMP-2 and MMP-9 protein expression, suppressing migration and invasion." (PMID 40490812, 2025). "In melanoma (B16-F10 and A375) cells, its ability to decrease MMP-2 and MMP-9 protein expression and suppress the Wnt/β-catenin pathway suggesting a therapeutic strategy for highly metastatic tumors." (PMID 40490812, 2025). "Our findings demonstrate that mTOR kinase inhibitors from three successive generations, particularly when used in combination with MEK1/2 inhibition, significantly reduce melanoma cell invasiveness and downregulate metalloproteinases MMP-2 and MMP-9." (PMID 40869090, 2025). "For instance, E-cadherin loss stabilizes c-JUN protein and upregulates target genes, such as MMP-9, MMP-14 and MMP-2, key factors in driving melanoma metastasis." (PMID 40399946, 2025). "In an A375 melanoma model, Lut treatment significantly reduced tumor weight and suppressed MMP-2 and MMP-9 expression, demonstrating its strong anti-cancer potential." (PMID 40563423, 2025). "As anticipated, ArcA treatment resulted in decreased protein and mRNA levels of both MMP-9 and MMP-13 across all melanoma cell lines." (PMID 39948552, 2025). "MMP-9 serves as an established marker of melanoma invasiveness, and MMP-2 functions as a pro-metastatic factor during melanoma progression." (PMID 40872552, 2025). "In melanoma cells, MMP-9 colocalizes with CD44, this interaction promotes the proteolytic activity of MMP-9 against type IV collagen." (PMID 39866233, 2025). "Exposure to melanoma-conditioned medium induced the upregulation of bFGF, CXCL-16, TIMP-2, and E-cadherin in NHKs, alongside downregulating TGF-β and MMP-9." (PMID 40869222, 2025). "In human melanoma (A375) cells, apigenin down-regulates STAT3 target genes matrix metalloproteinase 2 (MMP-2) and MMP-9, thereby suppressing tumor growth and invasion." (PMID 40490812, 2025). "The activities of two metalloproteinases, MMP-2 and MMP-9, were studied in the primary WM3211 and metastatic Mel-1359 and MEWO melanoma cell lines after 24 h and 48 h treatment with mTOR inhibitors and their combinations." (PMID 40869090, 2025). "In transdifferentiated A375 cells the melanoma markers MKI67, MITF, S100A4, S100A10, MMP2 and MMP9 were significantly downregulated." (PMID 40715046, 2025). "MMP9 is involved in the degradation of the ECM, but is also involved in neo-angiogenesis, cell migration, and formation of melanoma metastases." (PMID 40717170, 2025). "Several studies have shown that melanoma cells can express a specific pool of MMPs (MMP-1, MMP-2, MMP-9, MMP-13, and MT1-MMP) as well as their tissue inhibitors (TIMP-1, TIMP-2, and TIMP-3)." (PMID 39594665, 2024). "Apigenin stopped melanoma cell motility and invasion by downregulating STAT3 target genes (TWIST1, MMP-2, MMP-9, and VEGF)." (PMID 38398617, 2024).
melanoma (continued). "Prominent MMPs, including MMP-1, MMP-2, MMP-3, MMP-9, MMP-13, and MMP-14, have been shown to significantly contribute to the development of melanoma." (PMID 39769318, 2024). "For example, a study analyzing the expression of MMPs in melanoma found that MMP-1, MMP-2, MMP-3, MMP-7, MMP-9, and MMP-13 showed increased levels in melanoma tissues compared to normal tissues." (PMID 39200315, 2024). "After quercetin therapy, melanoma cells downregulate STAT3-targeted genes MCL-1, MMP-2, MMP-9, and VEGF, which increase cell proliferation, migration, and invasion." (PMID 38398617, 2024). "This MMP‐9‐dependent H3NT proteolysis is critical for establishing an active state of gene transcription during osteoclast differentiation and melanoma development." (PMID 38600695, 2024). "A possible similar activation of keratinocytes surrounding melanoma has been suggested by in vitro evidence that medium conditioned by melanoma cells stimulates the production of MMP3, MMP9, and MMP14 by Hacat cells while lowering TIMP expression." (PMID 38473275, 2024). "Solid‐state antibody chip results, including 105 antibodies, showed that GC‐7 and GL‐1 affected the expression of melanoma cytokines, among which ANG, IGFBP3, CSF2, CD71, CXCL1, and MMP9 were the most significant." (PMID 38952061, 2024). "A375 melanoma cells were stimulated with LL-37, and the mRNA expression of CXCL5, IL23A, MMP1, and MMP9 were evaluated in vitro." (PMID 36980564, 2023). "It reduces the migratory ability of melanoma cells through the regulation of E‐cadherin/vimentin and MMP‐2/MMP‐9 expression." (PMID 37038620, 2023). "The downregulation of STAT3-targeted genes MCL-1, MMP-2, MMP-9, and VEGF, which promote cell growth, migration, and invasion, have been identified in melanoma cells after quercetin treatment." (PMID 36829966, 2023). "Apigenin inhibited melanoma cell migration and invasion by downregulating STAT3 target genes (TWIST1, MMP-2, MMP-9, and VEGF)." (PMID 36829966, 2023). "Luteolin inhibited the proliferation and induced the apoptosis of melanoma cells by downregulating MMP-2 and MMP-9 expression through the PI3K/AKT pathway." (PMID 36829966, 2023). "The lncRNAs—promoter of CDKN1A antisense DNA damage activated RNA (PANDAR) and SRA-like non-coding RNA1 (SLNCR1)—can also promote melanoma invasion through EMT regulation and upregulating MMP9." (PMID 35406721, 2022). "Melanoma and lymphoma cells in TIMP-3-/- mice had a higher metastatic ability, MMP-2 and MMP-9 expression levels." (PMID 36555545, 2022). "Several matrix metalloproteinases are expressed in melanoma, the tumor, and the peritumoral stroma, including MMP-1, MMP-2, MMP-9, MMP-13, and MMP-14." (PMID 35558554, 2022). "We demonstrated that CD248 expression in melanoma tumor cells is correlated with tumor cell-fibronectin interaction, FAK activation, MMP9 expression, cell migration, and VM." (PMID 36401329, 2022). "In conclusion, PCDH9, which is regulated by the circ 0084043-miR-134-5p axis, can suppress malignant biological behavior in melanoma and influence the expression levels of Pyk2, RAC1, Cyclin D1, MMP2, and MMP9." (PMID 36387162, 2022). "In melanoma cells, decline in ARSB increased expression of MMP-9 and pro-MMP2 due to inhibition of SHP2 and activation of phospho-ERK1/2." (PMID 36361933, 2022). "For example, one study showed that in murine melanoma cells, the interaction of DDR2 with collagen I resulted in increased expression of MMP2 and MMP9 via the intracellular ERK/NF-κB signaling pathway and promoted melanoma cell invasion." (PMID 36119516, 2022). "Other mechanisms involved the inhibition of cancer stem cells in one colorectal liver-metastatic model and suppression of MMPs (MMP2 and MMP9) in two lung metastatic models from SKOV-3 ovarian cancer and B16 melanoma." (PMID 36012338, 2022). "In human melanoma cells, expression of pro-MMP2 and MMP-9 was increased following ARSB silencing and was mediated by decline in SHP2 activity and increase in phospho-ERK1/2." (PMID 36361933, 2022).
melanoma (continued). "Another study also found that MMP-9 (Gelatinase-B, closely related to MMP-2) is able to clip histone H3 and regulate gene expression involved in melanoma formation." (PMID 36076910, 2022). "RA has also been reported to modulate MMP-2 and MMP-9 expression in vitro in a few cell lines, including T98G GBM cells, THP1 cells, and A375 melanoma cells." (PMID 34572134, 2021). "PI3Kγ induces metastasis through increasing the formation of PDGF-BB and improving the expression of MMP-9, uPA, VEGF, HIF-1α, and HIF-2α in PDAC and melanoma, respectively." (PMID 32902664, 2021). "Further, MMP‐9 also cleaves the MHC class I molecule, cell surface antigen‐presenting complex molecules, expressed in melanoma cells." (PMID 34486239, 2021). "Nonetheless, the growth and invasion of melanoma cells into the brain parenchyma relied primarily on the vascular co-option, controlled by the expression of the matrix metalloproteinases MMP-2 and MMP-9." (PMID 33466236, 2021). "In the current study, we found that DTL, MMP9, LINC00520, and ZSCAN16-AS1 were highly expressed in melanoma compared with normal melanocytes, whereas XIST and let-7a-5p showed the opposite trend." (PMID 33854593, 2021). "In the case of A375 human melanoma cells, MMP was down-regulated by Nanog overexpression, though the MMP was a membrane type 1 (MT1-MMP) and different from a secretion type MMP9." (PMID 33665763, 2021). "In the case of A2058 melanoma MMP-2 and MMP-9 expression was upregulated by various cytokines and inducers." (PMID 33732640, 2021). "Results showed that in the murine melanoma B16F10 cell line, API (150 mg/kg) presented antimetastatic activity by suppressing STAT3 phosphorylation and downregulating MMP-2, MMP-9, and VEGF pathways." (PMID 34239802, 2021). "The silencing of MAF MMP-9 expression reverses MAF capability to inhibit anti–PD-1 responses and increases the ratio of CD8+ T cell/Treg in melanoma in vivo." (PMID 34067929, 2021). "Lut exhibited a similar behavior in human melanoma cells (A375 cells), where it inhibits proliferation, induces apoptosis, and reduces the expression of MMP-2 and MMP-9 (in vitro and in vivo)." (PMID 33498927, 2021). "The results showed that compared with normal nevus tissues, LINC00520, ZSCAN16-AS1, MMP9, and DTL had higher expression in melanoma, whereas XIST had lower expression." (PMID 33854593, 2021). "Specifically, Schnaeker at al. found that melanoma cells contained cytoplasmic vesicles positive for MMP2 and MMP9 that were released via microtubules to induce tumor invasion." (PMID 34071761, 2021). "B7-H3 induces its facilitating effects on metastasis of melanoma, HCC, and osteosarcoma via potentiation of MMP-9." (PMID 32902664, 2021). "The anti-metastatic action of Api was also found in human melanoma cells (A375 cells), where Api reduces the MMP-2 and MMP-9 in a dose-dependent manner." (PMID 33498927, 2021). "Given the recent emphasis on the role of MMP9 and MMP7 during cancer cell migration, we next investigated the effect of ALOC-EO on the migration of B16F10 melanoma cells grown in vitro." (PMID 34360915, 2021). "Knockdown of HOTAIR suppresses motility of metastatic melanoma cell lines, which is manifested by decreased gelatinase activity of MMP2 and MMP9." (PMID 34638331, 2021). "In another study, crocin (250 and 500 μg/kg) attenuated VEGF, MMP-2, and MMP-9 expressions and TNF-α and IL-6 levels while it elevated IL-10 level in melanoma metastatic model in C57BL/6 mice." (PMID 34956439, 2021). "Current studies have shown that the metastasis of melanoma is related to the expression of certain genes and the activation of certain pathways, such as ABCB5 expression, lncRNA KCNQ1OT1, the MMP-9 signaling pathway, and the HGF-MET signaling pathway." (PMID 34582363, 2021).
melanoma (continued). "We observed high levels of proteolytically active MMP-9 concurrently with very low levels of melanoma-derived TIMP-1 at the time of collagen IV dissolution, exclusively when melanoma cells were integrated into SR and expressed Tspan8." (PMID 32455575, 2020). "Surprisingly, MMP-9 and MMP-3 transcripts were increased in invading melanoma cells that have penetrated the DEJ, in comparison to melanoma cells still in contact with the DEJ." (PMID 32455575, 2020). "TAP-nanoemulsion triggered apoptosis of human malignant melanoma in the lung by inhibiting Bcl-2, cyclins D1 and E, NF-κB, ERK, MEK, and MMP-1 and MMP-9 and increasing cleaved caspase-9 and caspase-3, ATM, and p21." (PMID 32908627, 2020). "We showed earlier that Snail upregulates the activities of MMP-9 and MMP-14 in B16F1 melanoma cells." (PMID 32629890, 2020). "MMP-9 and MMP-3 were mainly expressed by keratinocytes whereas TIMP-1 was mainly expressed by Tspan8+ melanoma cells." (PMID 32455575, 2020). "Activities of two metalloproteinases: MMP-2 and MMP-9 were studied in the primary (WM793, WM115) and metastatic (Lu1205, WM266-4) melanoma cell lines after 24-h and 48-h treatment with protein kinase inhibitors and their combinations." (PMID 31586300, 2020). "Consistent with its expression change in RNA-seq, we confirmed the downregulation of MMP9 at the mRNA and protein levels in both DLC1 KD and FOXK1 KD melanoma cells." (PMID 32214200, 2020). "Our results identified MMP9 as one of the downstream targets to mediate the roles of DLC1 and FOXK1 in promoting melanoma cell invasion and metastasis." (PMID 32214200, 2020). "To determine the downregulation of PD-L1 expression under SB-3CT treatment through the MMP2/9 inhibition, we knocked down (KD) MMP2 or MMP9 with two shRNAs in SK-MEL-28 and A375 melanoma cell lines, respectively." (PMID 32988398, 2020). "Mechanistically, DLC1 was essential for FOXK1 occupancy to the promoter region of MMP9, and both DLC1 and FOXK1 acted cooperatively to transactivate MMP9 expression for melanoma invasion and metastasis." (PMID 32214200, 2020). "It was demonstrated that melanoma MMP-9 and MMP-2 play a fundamental role in the degradation of the ECM, thus, favoring melanoma spreading towards the surrounding tissues until the formation of distant metastases." (PMID 32392801, 2020). "Taken together, the data suggest that DLC1 and FOXK1 function in a cooperative manner to transactivate MMP9 promoter activity as well as MMP9 functions downstream of DLC1 and FOXK1 to promote melanoma invasion in vitro." (PMID 32214200, 2020). "According to previous reports, laminarin suppresses proliferation, colony formation, and migration of human melanoma cells by inhibiting matrix metalloproteinase-2 (MMP-2), MMP-9, and the p-ERK1/2 signaling cascade." (PMID 32182828, 2020). "Additionally, high MMP9 expression in metastatic melanoma cells may be maintained by this axis." (PMID 31569419, 2019). "Given that MMP9 is also regulated by miRs, the differential miR expression in CD133(+) versus CD133(−) melanoma cells or after Dox-induced CD133 expression will be further examined." (PMID 31623313, 2019). "We demonstrated previously that SLNCR1 binds to AR and recruits it to the MMP9 promoter and that SLNCR1 and AR are required for transcriptionally upregulating MMP9 expression and promoting melanoma invasion." (PMID 31116991, 2019). "Zymography used to measure the activity of metalloproteinases in melanoma cells revealed a significant difference between MMP-2 and MMP-9 activities in N-cadherin knocked-down cells in all tested cell lines in comparison with untreated ones." (PMID 29492694, 2018). "Among human melanoma cells, MMP-2 and MMP-9 have attracted attention in the recent years, especially with regard to cutaneous, eye, and oral melanomas." (PMID 29492694, 2018). "Median time to progression (TTP) and progression free survival (PFS) in 28 patients with melanoma according to BRAF and MMP-9." (PMID 30154717, 2018).
melanoma (continued). "Relative to the melanoma cells, in this case pretreatment with extract also significantly decreased the levels of IL-8, IL-6, MMP-2 and MMP-9." (PMID 28264501, 2017). "Actually, MMP-9 plays an important role in melanoma invasion and PTTG1 has been shown to positively regulate the expression levels of MMP-9." (PMID 29371923, 2017). "Mosaic vessel and VM channel formation in a B16F10 mouse melanoma model are reduced by thalidomide which inhibits expression of VEGF, NFκB, PCNA, MMP-2 and MMP-9." (PMID 29112161, 2017). "RT-PCR documented mRNA expression in all the melanoma cell lines analyzed (WM115, WM266.4, and the positive controls M10 and M14) for VEGF, FGF2, CDH2, CDH5, MMP-2, MMP-9, and the two isoforms of MCAM/MUC18." (PMID 28107182, 2017). "Our further analysis showed that KMT2A knockdown suppressed the expression of MMP2, MMP9 and promoted the cleavage of Caspase3/Caspase7/Caspase9 and PARP in melanoma cells, and repressed the expression of hTERT and the Nanog/oct-4/sox-2 stem cell markers." (PMID 28726783, 2017). "In melanoma cells or ovarian cancer cells, p38 MAPK promotes cell migration and invasion through regulation of MMP9." (PMID 27286263, 2016). "Protein and mRNA levels of MMP-9 were tested in A375, A2058, M14 and MEWO melanoma cell lines by ELISA test and RT-qPCR, respectively." (PMID 27115178, 2016). "Over expressions of MMPs including MMP-9 and MMP-2 plays a pivotal role in melanoma migration and invasion by stimulating degradation of the extracellular matrix." (PMID 26968952, 2016). "In vitro validation showed that CpG-2 hotspot region was hypermethylated in the A375 melanoma cell line with highest mRNA and protein levels of MMP-9, while low methylation levels were observed in the MEWO cell line where MMP-9 was undetectable." (PMID 27115178, 2016). "In the present study we show that CoQ0 treatment significantly inhibits melanoma migration and invasion by down-regulating MMP-2, MMP-9 and up-regulating TIMP-1 and TIMP-2 expressions." (PMID 26968952, 2016). "A similar inhibition of the upregulation of MMP-2 and MMP-9 by PRO has also been reported in nasopharyngeal carcinoma, pancreatic cancer, gastric adenocarcinoma, melanoma, prostate cancer and of MMP-9 in medulloblastoma and infantile hemangioma." (PMID 27899953, 2016). "When the melanoma samples were stratified in high, moderate and low group according the levels of MMP-9 expression, the CpG-2 region was hypermethylated in the MMP-9 high-expression melanoma samples compared to other groups, including melanocyte controls." (PMID 27115178, 2016). "In our previous study, we demonstrated that TRAF6 is overexpressed in melanoma and regulates melanoma metastasis through the ubiquitination of CD147 to regulate the expression of MMP-9." (PMID 27791197, 2016). "The aim of presented study was to evaluate the clinical utility of serum concentrations of VEGF, MMP-2, MMP-9, TIMP-1, and YKL-40 in patients with melanoma at locoregional stage." (PMID 26002577, 2015). "Only several publications have concerned the evaluation of the utility of measurements of VEGF, MMP-2, MMP-9, TIMP-1, and YKL-40 in serum in melanoma; what is more, the results are controversial." (PMID 26002577, 2015). "So far, published data has demonstrated that the tissue over-expression of VEGF, MMP-2, MMP-9, and TIMP-1 has an adverse effect on the course of the disease and survival of melanoma patients." (PMID 26002577, 2015). "The concentrations of VEGF, MMP-9, TIMP-1, and YKL-40 were significantly higher in patients with melanoma than in control group." (PMID 26002577, 2015).